SNORD116-28 (small nucleolar RNA, C/D box 116-28)
Synonyms: HBII-85-28
Gene: Small nucleolar RNA gene on chromosome 15 (25,104,642 to 25,104,732, forward strand). Ensembl gene ENSG00000278123.
Homologues: Orthologues: chimpanzee SNORD116 (98% identical), rabbit SNORD116 (69% identical), mouse Gm22373 (52% identical), rat LOC120100337 (43% identical). Paralogues in human: SNORD116-25 (78% identical), SNORD116-27 (74% identical), SNORD116-30 (74% identical), SNORD116-26 (73% identical), SNORD116-29 (70% identical), SNORD116-2 (67% identical), SNORD116-20 (67% identical), SNORD116-22 (67% identical), SNORD116-4 (67% identical), SNORD116-6 (67% identical), SNORD116-8 (67% identical), SNORD116-14 (66% identical), and 20 more.